HIF1A (hypoxia inducible factor 1 subunit alpha)
Diseases named in the same sentence as HIF1A in open-access papers (continued):
Sharing a sentence is not in itself a finding about the gene and the disease.
COVID-19 (128 papers, 2020 to 2025). A disease caused by infection with severe acute respiratory syndrome coronavirus 2. "HIF-1α, a transcription factor primarily induced under hypoxic conditions, is implicated in COVID-19 prognosis and neuronal metabolic regulation." (PMID 41202111, 2025). "Proteomic studies in patients with Long COVID-19 point to increased transcription of proteins linked to tissue remodeling and sustained inflammation, many of them regulated by HIF-1α." (PMID 40362439, 2025). "Severe cases of COVID-19 are commonly distinguished by hypoxemia and substantial endothelial dysfunction, conditions that are closely linked to the activation of HIF-1α." (PMID 40362439, 2025). "MLCs demonstrated an up-regulation of fibrosis-associated genes, such as VEGFA and HIF1A in PPASC compared to severe COVID-19." (PMID 38259488, 2023). "Quercetin has been reported to influence SARS-CoV-2 infection and COVID-19-associated cancer progression via suppression of HIF-1a and mTOR." (PMID 37704909, 2023). "By critically examining the influence of chronic hypoxia on susceptibility to and severity of COVID-19, the question can be redirected as to the role that the HIF-1α molecule plays on SARS-CoV-2." (PMID 36091390, 2022). "The rs11549465 variant of HIF-1α impacts breast cancer metastasis and is associated with COVID-19 susceptibility." (PMID 36091390, 2022). "HIF1α also induces the expression of LDH causing an increase in the conversion of pyruvate into lactate (a biomarker of a poor COVID-19 prognosis), further decreasing the pH, and further compromising innate defenses." (PMID 34395368, 2021). "Collectively, our data suggest that SARS-CoV-2 infection is highly associated with the pathways of HIF-1α, immune, and metabolism in COVID-19 patients’ blood samples." (PMID 34408131, 2021). "Another area in which MMPs and NRP could cooperate to accelerate COVID-19 damage is angiogenesis which is implicated along with Hypoxia-Inducible Factor-1α (HIF-1α) in COVID-19." (PMID 38803919, 2024). "Indeed, adverse effects of HIF-1α associated with activation on infection and pro-inflammatory responses, epileptogenesis, and pronounced and persistent defects of B cells in COVID-19 patients have also been reported." (PMID 36983445, 2023). "Additionally, other inflammation-related molecules shared between OA and COVID-19, such as these encoded by HIF1A, CXCL10, and CTSB, contribute to the same pathophysiological bonfire." (PMID 38020136, 2023). "In addition, emergency myelopoiesis occurs in critically ill COVID-19 patients, with augmented expression of HIF1α and its associated transcriptional targets." (PMID 35401519, 2022). "Since acute tubular necrosis is one of the most common changes observed in patients with AKI triggered by COVID-19, the increase in HIF-1α may be protective against the nephrological damage caused by the disease." (PMID 36439786, 2022). "Moreover, an association of the rs11549465 variant of HIF-1α with COVID-19 susceptibility was recently discovered." (PMID 36091390, 2022). "Moreover, an association of rs11549465 variant of HIF-1α with COVID-19 susceptibility has been reported." (PMID 36091390, 2022). "The presence of TNF-α, IL-1β, IL-6, and HIF-1α are associated with the COVID-19 cytokine storm." (PMID 34484241, 2021). "Our previous reports have revealed thrombosis due to hypoxia is centrally regulated by a complex network of coagulatory and inflammatory processes, critically linked through HIF-1α.24Conceivably, COVID-19 pathogenesis also witnesses inflammation–coagulation–hypoxemia convolutions." (PMID 33354650, 2020). "Therefore, it is tempting to speculate that the formation of monocyte–T cell and monocyte–NK cell complexes could be mechanistically associated with the upregulation of HIF1A in the monocytes of convalescent COVID-19 patients." (PMID 38391913, 2024).
COVID-19 (continued). "This analysis of the change in HIF1A expression over time confirms our hypothesis that the degree of the upregulation of HIF1A in monocytes in early convalescence (2 weeks after disease resolution) is linked to the severity of previous COVID-19 disease symptoms." (PMID 38391913, 2024). "Also, we hypothesized that the expression of CD147 and CyPA could be increased by HIF-1α activated by COVID-19, suggesting risk factors for long-term COVID-19 complications for cancer patients." (PMID 37016434, 2023). "Thus, subjects with HIF1α-associated PPG syndromes may benefit from an inherent protective effect against COVID-19." (PMID 34684070, 2021). "HIF-1α has been identified as a crucial regulator in the pathophysiology of COVID-19 owing to its significant role in coordinating metabolic adaptation, inflammatory responses, and vascular remodeling under conditions of low oxygen tension." (PMID 40362439, 2025). "In conclusion, we demonstrated the downregulation of HIF1A and GLUT1 in NK cells from patients with severe COVID-19 and provided evidence of their association with clinical outcomes." (PMID 40927375, 2025). "In the context of COVID-19, β-catenin has been shown to inhibit macrophage proliferation and repopulation through the β-catenin-HIF-1α axis by disrupting mitochondrial adaptation; however, it can also promote macrophage inflammatory activity." (PMID 40136643, 2025). "It is well established that COVID-19 induces systemic and neuroinflammation, accompanied by elevated ROS and cytokine signaling, all of which can upregulate HIF-1α." (PMID 41202111, 2025). "NK cells from severe COVID-19 patients showed downregulation of HIF1A and GLUT1, and upregulation of NFKB1 (P < 0.05)." (PMID 40927375, 2025). "In contrast, HIF1A expression was 2.6-fold lower in NK cells of patients with severe COVID-19 (0.45 [0.07-1.35]) than in the control group (1.17 [0.47-1.63]), P = 0.001." (PMID 40927375, 2025). "This study’s critical analysis highlights the key role of the hypoxia-inducible transcription factor HIF-1α in the pathophysiology of COVID-19, emphasizing its dual influence on inflammatory processes, metabolic adaptations, and post-acute complications." (PMID 40362439, 2025). "The potential for targeting HIF-1α therapeutically in COVID-19 is complex, requiring further investigation to clarify its precise role and translational applications." (PMID 40362439, 2025). "Post-mortem analyses of COVID-19 lungs notably reveal that HIF-1α is overexpressed and colocalized with SARS-CoV-2 nucleocapsid proteins in pneumocytes, suggesting direct viral manipulation of hypoxic pathways." (PMID 40362439, 2025). "In severe COVID-19, we observed significant imbalances in HIF-1α/HIF-3α and HIF-2α/HIF-3α ratios, suggesting a breakdown in hypoxic adaptation and the onset of pathological inflammation." (PMID 40702494, 2025). "Nonetheless, a reanalysis of data generated by other studies supports our major conclusion that HIF1A serves as a robust retrospective marker for COVID-19 disease severity." (PMID 38391913, 2024). "This revealed HIF1A as a severity-sensitive long-term immunological scar in circulating monocytes of convalescent COVID-19 patients." (PMID 38391913, 2024). "Taken together, this study has identified HIF1A as an immunological scar of COVID-19, which is sensitive to prior disease severity and which outlasts the half-life of the affected innate immune cell subsets." (PMID 38391913, 2024). "We then correlated the change in HIF1A expression in the T cell–monocyte cluster over time (log2FC) with COVID-19 severity scores." (PMID 38391913, 2024). "This difference in expression was also evident within the COVID-19 group, with elderly individuals presenting higher HIF1A mRNA expression." (PMID 39791730, 2024). "We concluded that high HIF1A expression is a general feature of all monocytes in recently recovered COVID-19 patients and cannot be attributed to a specific dysregulated subpopulation." (PMID 38391913, 2024).
COVID-19 (continued). "It supports the conclusion that HIF1A acts as a severity-sensitive immunological scar in convalescent COVID-19 patients." (PMID 38391913, 2024). "Consistent with other reported COVID-19 clinical data, HIF-1α levels increased in PSCV-infected MH-S and THP-1 cells, as well as in CMPSV-stimulated MRC-5 cells." (PMID 38914619, 2024). "We have discussed in detail the significant role of HIF1A in the development of COVID-19 and OSA patients." (PMID 38443855, 2024). "With single-cell RNA sequencing, we reveal a role for hypoxia-inducible factor 1-alpha (HIF1A) as a severity-sensitive long-term immunological scar in circulating monocytes of convalescent COVID-19 patients." (PMID 38391913, 2024). "By contrast, transcriptomic sequencing of transmigrated human neutrophils sampled from nasopharyngeal swabs or broncho-alveolar fluid in COVID-19 revealed upregulation of the HIF1α downstream target gene VEGFA, indicating successful HIF1α protein translation." (PMID 39469705, 2024). "This leads to the conclusion that HIF1A serves as not only an immunological scar of SARS-CoV-2 infection but also a retrospective indicator of previous COVID-19 disease severity in convalescence." (PMID 38391913, 2024). "Elevated glucose and glycolysis (hyperglycolysis) are observed in severe COVID-19 as a mechanism to promote viral replication, through ROS stabilization of HIF1α." (PMID 36768847, 2023). "In severe COVID-19 cases, altered bioenergetic profiles of monocytes in response to elevated HIF-1α are a relevant molecular marker." (PMID 38049897, 2023). "Metabolic shift in immune cells of COVID-19 infected lungs is triggered by HIF-1α, which was observed on both transcriptomic and proteomic levels." (PMID 37008787, 2023). "One of the presenting features of COVID-19 is hypoxia, and the induction of hypoxia-inducible factor 1-α (HIF1-α) is considered an important component of SARS-CoV-2 infection." (PMID 37835544, 2023). "ECs in the lungs of COVID-19 patients exhibit an increase in both hypoxia-inducible factor 1-alpha (HIF-1α) and glucose transporter protein type 1 (GLUT1) expression, confirming local hypoxic stress as a potential trigger for this pathogenic process." (PMID 36979908, 2023). "Studies have demonstrated the role of CTNNB-2 (β-catenin) in inflammation and repair promoted by alveolar macrophages during COVID-19, finding a relationship between this protein and HIF-1α in the sense of intensifying inflammatory activity." (PMID 36992415, 2023). "The transcription factor hypoxia-inducible factor 1-alpha (HIF-1a) can induce glycolysis, leading to a pro-inflammatory state in monocytes infected with COVID-19." (PMID 36852336, 2023). "HIF-1α is activated and translocated to the nucleus upon hypoxic conditions, and it has been shown that COVID-19 patients present massive hypoxia due to vasoconstriction and coagulopathy." (PMID 36992454, 2023). "Increased HIF-1α levels have been reported in cardiovascular tissue regions that display less cellular damage postmortem in COVID-19 patients, suggesting that HIF-1α activation was correlated with tissue protection." (PMID 37417946, 2023). "Nine of ten anti-COVID-19 core targets (HIF1A, EGFR, CASP3, AKT1, MAPK1, MAPK3, HSP90AA1, mTOR, and IL-6) followed the pathways in cancer." (PMID 36817449, 2023). "In line with this, we determined the Hypoxia-inducible factor 1-alpha (HIF-1α) mRNA expression in PBMCs from COVID-19 patients to corroborate the hypoxemia condition in these patients." (PMID 35327634, 2022). "Patients with COVID-19 often develop shortness of breath and dyspnoea which triggers local hypoxia and induces HIF-1α activation and VEGF production." (PMID 36091390, 2022).
COVID-19 (continued). "In our current study, we found that HIF1A expression significantly increased in the alveolar macrophages of patients with COVID-19." (PMID 35844544, 2022). "ROS not only create an oxidative milieu within cells, but also directly inhibit HIF-1α prolyl hydroxylation and degradation resulting in overexpression of HIF-1α in the hamster COVID-19 model pulmonary tissue analyzed." (PMID 36614003, 2022). "In severe COVID-19 patients, HIF1α expression is higher in peripheral and BALF neutrophils, along with upregulated genes encoding proteins of glycolysis, glycogen metabolism, and gluconeogenesis and lower expression of genes of oxidative phosphorylation." (PMID 35401519, 2022). "Ultrastructural mitochondria alterations are likely correlated with the elevated oxidative stress documented herein by TBARS and HIF-1α overexpression in COVID-19 placentae." (PMID 35327436, 2022). "HIF-1α induced monocyte metabolic disturbance in patients with COVID-19 directly suppresses T cell responses and reduces epithelial cell survival." (PMID 35663983, 2022). "These events are recognized as major COVID-19 pathogenic mechanisms suggestive of an altered OxS regulation triggered by SARS-CoV-2 that we confirmed with placental TBARS and HIF-1α overexpression." (PMID 35327436, 2022). "During hypoxic conditions of COVID-19, the HIF-1α transcription factor subunit has a risky role in the expression of the COVID-19 receptor gene (ACE-2 gene), and hypoxia causes endothelium damage and upregulation of adaptive and innate immunocytes." (PMID 36045713, 2022). "Although further research is needed, our data suggest that probably CD39 expression increases in severe COVID-19 patients due to the activation of HIF-1α and RIG-I pathways." (PMID 35173744, 2022). "Taken together, these findings suggest a prominent role of HIF1A in COVID-19 not only as a key molecule for the management of tissue hypoxia but also as a coordinator of infection control and controller of SARS-CoV-2 invasiveness." (PMID 35163504, 2022). "The recognition of HIF-1α and IL-6, as being important pathogenetic factors in COVID-19, gives renalase a potential, yet unrecognized, role in COVID-19." (PMID 36132227, 2022). "As a consequence of hypoxemia, HIF-1α mRNA was overexpressed in COVID-19 patients with respect to HC." (PMID 35173744, 2022). "We highlight the central role played by the HIF-1α signaling pathway in the pathophysiology of COVID-19." (PMID 36091390, 2022). "MiR-21-5p and miR-22-3p, both upregulated in COVID-19 patients, target several genes involved in cell signaling, cell proliferation and angiogenesis (e.g., HIF1A, MYC, SP1, SMAD7, VHL)." (PMID 36032130, 2022). "In conclusion, we have shown that the HIF-1α signaling pathway is activated in the COVID-19 hamster model along with a considerable accumulation of mitochondrial ROS." (PMID 36614003, 2022). "Recent reports indicate that living in high altitudes entails some degree of protection from SARS-CoV-2 infection/COVID-19, possibly by intermittent activation of HIF1α." (PMID 34684070, 2021). "Collectively, our results demonstrated that HIF-1α was induced in COVID-19 patients, elicited significantly in elderly patients, and activated upon the infections of SARS-CoV-2, VSV, or HSV-1 or the treatment of poly(I: C) in cultured cells." (PMID 34408131, 2021). "RNA sequencing shows that HIF-1α signaling, immune response, and metabolism pathways are dysregulated in COVID-19 patients." (PMID 34408131, 2021). "This indicates that PKM2 is important in COVID-19 severity via activation of HIF1α and the expression of inflammatory cytokines." (PMID 34240083, 2021). "According to RNA sequencing, COVID-19 patients have dysregulated HIF-1α signaling, immune response, and metabolism pathways." (PMID 35003073, 2021). "Since HIF1α is a transcription factor that acts as a trans regulator, we searched for HIF1α-regulated genes potentially involved in COVID-19 immunity." (PMID 33345622, 2021).
COVID-19 (continued). "On the other hand, the hypoxic and inflammatory microenvironment of COVID-19 can also induce hypoxemia in patients and directly upregulate HIF-1α expression." (PMID 34277453, 2021). "We also noted that similarly to HIF-1α, the level of IL-1β mRNA was much higher in PBMCs of COVID-19 patients related to healthy individuals." (PMID 34408131, 2021). "Lung cells from COVID-19 patients show expression of HIF1α, TLR2, TLR4, PFKFB3, CXCR1, −2 and −4, SOD2, PLAUR and other genes expressed in immature myeloid cells." (PMID 33345622, 2021). "We must also be aware that even in obesity, elderly, with other comorbidities and even COVID-19 survivors, HIF-1α has been reported to be upregulated compared to normal populations." (PMID 35003073, 2021). "Long noncoding RNAs (lncRNAs) regulates gene expression, which probably influences the COVID-19 progression by regulating HIF-1α." (PMID 34277453, 2021). "We found that HIF1A is increased in CD16+ monocytes in severe COVID-19 cases compared to healthy controls." (PMID 34108966, 2021). "We observed that HIF1α expression was lower as compared to the expression observed in COVID-19 patients." (PMID 33345622, 2021). "In spite of these useful effects of HIF-1α inhibition on COVID-19 symptoms, there is a challenge in this case returning to SARS-CoV-2 infection of endothelial and epithelial cells with ACE2 receptor." (PMID 33139969, 2020). "So, in this study the possible effect of the HIF-1α on the COVID-19 pathogenesis with emphasizes on its role on innate immunity response has been discussed." (PMID 33139969, 2020). "It was reported that HIF-1α can induce ACE2 upregulation in cardiac pericytes under prolonged hypoxic conditions, potentially increasing the risk of viral entry and associated damage in the myocardium during COVID-19." (PMID 40362439, 2025). "This article aims to address the controversies presented in the literature regarding the role of the HIF-1α subunit in the course of COVID-19, in addition to approaching possible therapies and encouraging the research development related to this important molecule of cellular metabolism." (PMID 40362439, 2025). "Importantly, many of these disorders have been demonstrated to be associated with severe SARS-CoV-2 infection, thereby suggesting the prognostic impact of HIF-1A on COVID-19." (PMID 38443855, 2024). "Interestingly, in a study performed in peripheral blood mononuclear cells (PBMCs), Tian and colleagues reported a significant increase in HIF1A mRNA in COVID-19 patients compared to healthy controls." (PMID 39791730, 2024). "Upregulation of hypoxia-related genes such as HIF1A has been observed in COVID-19 patients." (PMID 38391913, 2024). "Interestingly, the AUC was also associated with NDRG2, a target of HIF-1a signaling and regulator of apoptosis, suggesting NDRG2 as a possible regulator of AUC in the COVID-19 patients." (PMID 37918965, 2024). "Importantly, the public dataset also includes healthy control patients, therefore, not only enabling the verification of our findings so far but also allowing for a comparison of HIF1A expression between COVID-19 and healthy subjects." (PMID 38391913, 2024). "To additionally investigate HIF1A expression in healthy controls and to validate our results across a larger patient cohort, we took advantage of a publicly available scRNA-seq COVID-19 dataset that matched our study setup in terms of having multiple sampling time points." (PMID 38391913, 2024). "Importantly, we also found a correlation of the degree of HIF1A upregulation and the severity of previous COVID-19 symptoms." (PMID 38391913, 2024). "Building upon the significantly upregulated HIF1A expression observed exclusively in previously symptomatic COVID-19 patients, we further hypothesized that the degree of HIF1A upregulation in week 2 could be associated with the severity of former symptoms." (PMID 38391913, 2024).